UCHL1 (ubiquitin C-terminal hydrolase L1)
Diseases named in the same sentence as UCHL1 in open-access papers (continued):
Sharing a sentence is not in itself a finding about the gene and the disease.
melanoma (16 papers, 2011 to 2025). A malignant, usually aggressive tumor composed of atypical, neoplastic melanocytes. "Another putative KEAP1-NRF2-CUL3 gene, UCHL1 (ubiquitin C-terminal hydrolase L1), has also been implicated in different types of human cancer such as breast, melanoma, ovarian, colorectal, osteosarcoma, and gastric cancers, and multiple myeloma." (PMID 29306329, 2018). "Reduced UCHL1 was associated with worse outcome in primary melanoma." (PMID 27206673, 2016). "A reduction in UCHL1 expression has previously been associated with poor survival in melanoma." (PMID 22028813, 2011). "This suggests a dual role for UCHL1 in both PD and melanoma, emphasizing its significance as a potential therapeutic target in these conditions." (PMID 40860809, 2025). "UCHL1 overexpression in melanoma cells activates UPS-mediated degradation, consequently inhibiting microphthalmia-associated transcription factor (MITF) expression and reducing melanin production." (PMID 40860809, 2025). "UCHL1 promotes the growth of melanoma cells by activating the activity of protein kinase and activating the signal pathway." (PMID 35546675, 2022). "UCHL1 is an oncogene, and a recent study showed that high expression of UCHL1 is correlated with worse overall survival in melanoma patients." (PMID 34326324, 2021). "Suppression of UCHL1 was postulated as an early step of melanoma development, given that melanocytes present high levels of UCHL1, while benign nevi lack this protein." (PMID 27206673, 2016). "We confirm previous reports that COL1A2, THBS1, TNFRSF10D and UCHL1 are highly methylated in melanoma, thus providing further evidence that these genes are highly important in melanocytic neoplasia." (PMID 22028813, 2011). "Summary of COL1A2, THBS1, TNFRSF10D and UCHL1 methylation in melanocytes, melanoma cell lines, fresh-frozen melanoma tumors and other cancer cell lines." (PMID 22028813, 2011). "The current study details UCHL1 (ubiquitin COOH-terminal esterase L1) inactivation by promoter methylation in melanoma." (PMID 22028813, 2011). "The UCHL1 promoter appeared to be 8-fold more methylated in melanoma cell lines compared to melanocytes, and 4-fold more methylated in the 30 fresh tumors compared to the same control." (PMID 22028813, 2011). "On the contrary, upregulation of TYRP1, CNTN1 and UCHL1 in melanoma could be reversing malignant conditions." (PMID 27206673, 2016). "The melanoma cell lines with high UCHL1 mRNA expression have <20% methylation." (PMID 22028813, 2011). "This conclusion was supported by a loss-of-function study on the murine model of pulmonary metastasis using the murine melanoma cell line, B16F10, which originally showed the higher endogenous expression of UCHL1." (PMID 25615526, 2015). "The epigenetic cytosine-phosphate-guanine (CpG) DNA hypermethylation of UCHL1/PGP 9.5 promoter is a well-known mechanism responsible for partial or complete silencing of the expression within tissues and was well demonstrated in melanoma cell lines and patients, respectively." (PMID 30148172, 2018). "A majority (56%) of the melanoma cell lines had no UCHL1 mRNA expression, which correlated with a high degree of UCHL1 promoter methylation in 79% of them (5% of methylation in melanocytes compared to an average of 42% in melanoma cell lines, range = 29–95%)." (PMID 22028813, 2011).
ischemic stroke (15 papers, 2016 to 2025). A stroke disorder caused by obstruction of blood flow to the brain, due to thrombotic (local blood clot formation) or embolic (due to a blood clot or other material traveling from another site) event. "In this study, we charted the temporal profile of GFAP, NFL, t-tau, and UCHL1 concentrations in plasma following an ischemic stroke by analyzing daily blood samples collected throughout the first week after symptom onset." (PMID 40900222, 2025). "As compared with wild‐type controls, the UCHL1 C152A knock‐in mice show decreased accumulation of ubiquitinated proteins and axonal injury after MCAO, suggesting that UCHL1 plays a critical role in maintaining axonal function after ischemic stroke." (PMID 38778460, 2024). "UCHL1 activity is of great importance for function after ischemic stroke, and the C152 site of UCHL1 plays a critical role in functional recovery after cerebral ischemia." (PMID 32089771, 2020). "Additionally, inhibition of miR-181b, lncRNA-Fendrr, lncRNA MIAT and lncRNA SNHG3 was determined to play neuroprotective roles in treating cerebral I/R injury and ischemic stroke by promoting UCHL1/HERC2 expression or accelerating REDD1/HDAC3 ubiquitination degradation." (PMID 38515760, 2024). "Notably, in mouse ischemic stroke models (middle cerebral artery occlusion) in vivo, miR-181b expression is downregulated in response to ischemic exposure, thus ameliorating poststroke neurovascular injury by increasing ubiquitin carboxyl-terminal hydrolase isozyme L1 (UCHL1) and HSPA5 expression." (PMID 38515760, 2024). "UCHL1 has been described as a marker of traumatic brain injury in the early post-injury period and has also been found to be increased in serum from patients with ICH compared to ischemic stroke." (PMID 36776230, 2022). "However in previous works with rat models, UCHL1 was found to have increased in cerebral spinal fluid or serum following an ischemic stroke but not in hemorrhagic stroke." (PMID 36776230, 2022). "Both inhibitor and shRNA of UCHL1 significantly reduced the ratio of LC3‐II/total LC3, which contributed to neuronal survival after ischaemic stroke, but did not alter the level of Cl‐caspase‐3." (PMID 28726275, 2017).
COVID-19 (14 papers, 2021 to 2025). A disease caused by infection with severe acute respiratory syndrome coronavirus 2. "As NfL, GFAP, UCHL-1, and Tau protein are associated with senescence, the statistical analysis among severe COVID-19, mild COVID-19, and health control group biomarkers was matched by decade of life." (PMID 37996731, 2024). "In fact, UCHL1 is a plasma biomarker that is elevated after blood–brain barrier disruption, and has been associated with severe COVID-19 outcomes." (PMID 36362378, 2022). "We reported here the association between the peripheral biomarker UCHL1 and severe disease of COVID-19." (PMID 34504487, 2021). "In influenza, UBE2S, USP53, and TIMM10 were observed in this category, while in COVID-19, UBE2T, UBE2C, DTL, MT-ND2, UCHL1, and UBA52 were implicated." (PMID 41020849, 2025). "We observed significantly lower levels of MMP-9 at day 1 in pediatric COVID-19 patients compared to controls (28.14 (16.4,38.6) vs. 100.3 (67.2,882.6) μg/ml, p = 0.005) and UCHL-1 [2.2 (0.7,16.3) vs. 35.2 (10.7,54.3) ng/ml, p = 0.013)." (PMID 39352661, 2025). "Overall, UCHL1 is closely related to the severity and prognosis of COVID-19 in both the acute and late stages, suggesting its potential as a drug target for COVID-19." (PMID 39201608, 2024). "In severe COVID-19 patients, UCHL1, along with other neurological biomarkers, such as GFAP, NfL, and TAU, can serve as an early predictor of poor prognosis." (PMID 39201608, 2024). "UCHL1 is an important neurological biomarker in the study of COVID-19, and its level is higher in COVID-19 patients than in non-COVID-19 controls with mild cognitive impairment (MCI) or AD." (PMID 39201608, 2024). "By analyzing the publicly available transcriptome datasets, GSE152418 and GSE190496, from COVID-19 patients and healthy controls, we observed the significant differential expression patterns of the UCHL1 gene in both datasets." (PMID 39201608, 2024). "Another study indicated that autoantibodies, including those against UCHL1, were more prevalent in COVID-19 patients than in controls, particularly among those experiencing altered consciousness." (PMID 39201608, 2024). "Within the COVID-19-positive participants, UCHL1 levels were higher at month 3 after diagnosis compared to month 1 or month 2 (p = 0.027)." (PMID 37284701, 2023). "Here, we observed higher levels of Ubiquitin C-Terminal Hydrolase L1 (UCH-L1) in severe COVID-19 patients than in the mild group (p ≤ 0.05)." (PMID 36362378, 2022). "To further elaborate the role of UCHL1 in COVID-19, we reviewed human studies investigating the use of serum UCHL1 as biomarker for brain injury." (PMID 34504487, 2021). "In the GSE152418 dataset, the expression level of UCHL1 in peripheral blood mononuclear cells (PBMCs) was significantly upregulated in COVID-19 patients (log2(FC) = 4.79, p-value = 7.2 × 10−6), consisting of 12 severe cases, 4 mild cases, and 1 convalescent case." (PMID 39201608, 2024). "Similarly, in the GSE190496 dataset, UCHL1 expression also showed a significant upregulation trend (log2(FC) = 4.67, p-value = 0.025) in lung tissue cell samples of COVID-19 patients (11 postmortem cases and 2 survivors)." (PMID 39201608, 2024). "Finally, we constructed a risk signature in three genes (MET, UCHL1, IGF1) correlated to COVID-19 in IPF by conducting Lasso Cox Regression analyses." (PMID 36147332, 2022). "Together, we found that UCHL1 expression used as a biomarker in the peripheral blood can predict the disease development of COVID-19, although the potential mechanism by which this molecule participates in the pathogenesis of COVID-19 requires further investigations." (PMID 34504487, 2021). "Therefore, the purpose of our study was to investigate whether neurofilament light (NfL), glial fibrillary acidic protein (GFAP), tau, or ubiquitin carboxyl-terminal esterase L1 (UCHL1) are elevated in the plasma of young adults with mild COVID-19 symptoms." (PMID 37284701, 2023).
COVID-19 (continued). "Twelve participants diagnosed with COVID-19 had plasma collected 1, 2, 3, and 4 months after diagnosis to determine whether NfL, GFAP, tau, and UCHL1 concentrations increased over time or whether plasma concentrations were elevated compared with COVID-19-naïve participants." (PMID 37284701, 2023). "Once the connection between UCHL1 and the neurological complication of COVID-19 is firmly established, the presence of this molecule could be used for the early diagnosis of neurological disorder caused by SARS-CoV-2 attack and favor the therapeutic intervention of COVID-19 patients." (PMID 34504487, 2021). "The dynamic-perturbation-network-based drug-repurposing method applied to the drug–target module identified UCHL1 as a potential drug target and suggested pregnenolone and BRD-K87426499 as promising drug candidates for COVID-19." (PMID 39201608, 2024). "To investigate the effects of COVID-19 on BIMs, we examined systemic levels of six previously validated BIMs—MAP2, NSE, GFAP, S100B, Syndecan-1 and UCHL1." (PMID 34838058, 2021). "Firstly, we confirmed the normalized gene expression profiles of UCHL1 measured by RNA-seq in each cohort with or without COVID-19." (PMID 34504487, 2021). "However, in STC exposed to COVID-19 plasma, we observed apoptotic cell death in both UCHL1 positive and UCHL1 negative cells (white arrows)." (PMID 37200377, 2023). "The difference in UCHL1 findings may also be because arterial blood was taken on the day of admittance to the ICU in that study, whereas venous blood was taken from our participants starting 3–4 weeks after COVID-19 diagnosis." (PMID 37284701, 2023). "Based on our data, it appears that mild COVID-19 in young adults does not increase plasma NfL, GFAP, tau, or UCHL1." (PMID 37284701, 2023). "Although sex differences were found in our small population, it does not appear that young healthy persons with mild COVID-19 symptoms experience changes in the brain injury biomarkers NfL, GFAP, tau, or UCHL1." (PMID 37284701, 2023).
non-small cell lung carcinoma (14 papers, 2004 to 2025). A group of at least three distinct histological types of lung cancer, including non-small cell squamous cell carcinoma, adenocarcinoma, and large cell carcinoma. "Recent reports demonstrated that UCHL1 plays a key role in dissemination of non-small cell lung cancer and an association of UCHL1 with β-catenin signaling pathway." (PMID 21999842, 2011). "Deregulation of UCHL1 has been observed in solid tumors such as pancreatic cancer, non-small cell lung cancer, colorectal cancer, osteosarcoma, and oesophageal cancer." (PMID 21999842, 2011). "Biomarkers of neurodegeneration, NfL, GFAP, tau and UCHL1 were measured in a cohort of up to 88 subjects at baseline and 21 days after the first of six cycles of paclitaxel and carboplatin chemotherapy, administered as therapy for the treatment of non-small cell lung cancer." (PMID 36114333, 2022). "Our previous studies have demonstrated that ubiquitin C-terminal hydrolase L1 (UCHL1), which is a member of the DUB family, could promote resistance to pemetrexed in non-small cell lung cancer (NSCLC) by up-regulating thymidylate synthase." (PMID 33718207, 2021).
Cognitive impairment (13 papers, 2016 to 2025). Abnormal cognition is characterized by deficits in thinking, reasoning, or remembering. "According to the GSEA phenotype analysis, APOE, BDNF, CACNA1A, COMT and UCHL1 were identified as the main genes associated with cognitive impairment (FDR q-value < 0.05)." (PMID 41301762, 2025). "The two markers had a good diagnostic performance across the AD spectrum, with UCHL1 showing the best capability to differentiate early AD (both preclinical and mild cognitive impairment) from SCD and MCI subjects." (PMID 37454217, 2023). "Abnormal function of UCHL-1 and inhibition of ubiquitin hydrolytic activity of UCHL-1 in AD mice disrupt the distribution of synaptic proteins increase the spine size of hippocampal neurons, decrease spine density, and exacerbate cognitive impairment." (PMID 36195875, 2022). "With respect to cognitive impairments, UCHL-1 was found to be required for neuronal synapse formation and maintenance of cognitive function." (PMID 36195875, 2022). "Additional, less consistently described features include epilepsy, cognitive impairment, facial myokymia, fasciculations, and reduced peripheral sensation, reflecting the widespread expression of UCHL1 in most neuronal cells." (PMID 32656641, 2020). "Therefore, we hypothesized that exercise activated the PI3K/Akt signaling pathway in the hippocampus of APP/PS1 mice, decreased the expression level of BACE1 and correspondingly increased the level of UCHL-1, thereby improving cognitive impairment in the AD state." (PMID 36195875, 2022). "These mice showed cognitive defects such as inhibition of LTP, and the protein level of UCHL1 was significantly decreased in hippocampus." (PMID 26881020, 2016).
diabetes (13 papers, 2015 to 2025). "Moreover, UCHL1 has been implicated in regulating apoptosis of β cells and diabetes progression in hIAPP-Tg mice." (PMID 31700166, 2020). "Since the Drosophila UCH gene (cg4265) is the homologous gene for human UCHL1, we employed UCH knockout (UCHKO) and UCH C93S knockin (UCHC93S), encoding a catalytic dead form of UCH, mutant fly lines to observe diabetes-related phenotypes." (PMID 38212312, 2024). "UCHL1 immunohistochemistry is extensively used to study peripheral axonopathy in mouse models of diabetes, primarily looking at the footpad innervation." (PMID 26222784, 2015). "Being able to visualize sensory and motor neurons in the same mouse is especially important, and our studies with the diabetes model and with hSOD1G93A-UeGFP mice demonstrate the versatile use of UCHL1-eGFP reporter line in two different disease paradigms." (PMID 26222784, 2015). "In this report, we used UCHL1-eGFP reporter line in two different disease paradigms: diabetes and motor neuron disease." (PMID 26222784, 2015). "For example, mice injected with streptozotocin (SZT) developed diabetes, and UCHL1 expression revealed significant axonopathy by 6 months." (PMID 26222784, 2015).
lymphoma (13 papers, 2007 to 2025). A malignant (clonal) proliferation of B- lymphocytes or T- lymphocytes which involves the lymph nodes, bone marrow and/or extranodal sites. "In general, UCHL1 is induced in B cells undergoing the GC reaction and is also highly expressed in lymphomas derived from GCB cells, providing an essential survival signal." (PMID 34681663, 2021). "The DUB UCHL1 has been found to be expressed in GC B cells and lymphoma cells, but the functional relevance of this expression of UCHL1 has not been determined." (PMID 31042473, 2019). "Both T and B lymphocytes labeling with CD 20 and UCHL-1 were found within this lesion confirming poly clonality and definitely excluding lymphoma." (PMID 17710239, 2007). "UCHL1 promotes cell survival and growth in B-cell malignancies, significantly influencing the Akt signaling pathway, crucial for cell proliferation and survival in cancers like lymphoma." (PMID 39199615, 2024).
nasopharyngeal carcinoma (13 papers, 2011 to 2026). A carcinoma arising from the nasopharyngeal epithelium. "A more recent study in nasopharyngeal carcinoma revealed a similar conclusion that UCHL1 promoter hypermethylation was validated in nasopharyngeal carcinoma tissues." (PMID 33585209, 2020). "Moreover, another member of UCHs family, UCHL1 was demonstrated as a tumor suppressor gene in nasopharyngeal carcinoma (NPC)." (PMID 33585209, 2020). "Similarly to the reports of other groups, for example, that 64.9% of serum samples had methylated UCHL1 methylation in nasopharyngeal carcinoma, the methylation frequency of UCHL1 in the present study was 56.1%." (PMID 26550574, 2015).
pancreatic cancer (13 papers, 2009 to 2023). "Particularly, overexpression of UCHL1 has been found in pancreatic cancers and it is associated with a poor prognosis, so the functional consequences of UCHL1 have yet to be determined." (PMID 22794276, 2012). "In contrary, promoter hypermethylation leading to silencing of UCHL1 has been reported in progression of squamous cell carcinoma as well as gastric cancer and in pancreatic cancer cell lines." (PMID 21999842, 2011). "Other stool biomarkers which may be useful in the early detection of pancreatic cancer are NDRG4 or UCHL1." (PMID 33114412, 2020). "The silencing of UCHL1 was discovered by cDNA microarrays and chemical genomic screening of head and neck squamous cell carcinoma as well as pancreatic carcinoma lesions and pancreatic carcinoma cells either left untreated or treated with demethylating agents." (PMID 19857250, 2009). "However, UCHL1 has been reported to be repressed by methylation in other cancers, such as primary head and neck squamous cell carcinoma and colorectal, ovarian and pancreatic cancers." (PMID 22794276, 2012). "For example, the genes SPARC, UCHL1, NPTX2, PENK, and PDAC were investigated in pancreatic cancer, where they were found to be hypermethylated in patients with pancreatic cancer." (PMID 34771655, 2021).